KRAS (KRas proto-oncogene, GTPase)
Diseases named in the same sentence as KRAS in open-access papers (continued):
Sharing a sentence is not in itself a finding about the gene and the disease.
cancer (continued). "Activating hotspot mutations in both the KRAS and PIK3CA oncogenes were present in both benign and malignant tumors." (PMID 36635367, 2023). "Various oncogenic driver mutations, including KRAS mutations, mediate the aggressiveness and EMT of cancer cells." (PMID 37762678, 2023). "In this regard, mouse cancer models tested the pharmacologic inhibition of KRAS G12C that led to an increased level of MHC-I expression on cancer cells and promoted TME infiltration by cDCs-1 and T-cells." (PMID 37511856, 2023). "An alternative avenue for targeting KRAS-driven cancer is to exploit oncogene-specific vulnerabilities." (PMID 37407562, 2023). "We designed universal pegRNAs which can correct all types of G12 and G13 KRAS mutations and confirmed that the universal pegRNA can correct endogenous KRAS mutations in HEK293T/17 cells and three human cancer cell lines." (PMID 37391511, 2023). "KRAS is the most commonly mutated RAS family gene and is a primary cause of the occurrence of several types of cancer." (PMID 37391511, 2023). "Combining SHP2 and MAPK pathway inhibitor for treating KRAS-mutant cancers is a rationale strategy in the clinic." (PMID 37808191, 2023). "Immunotherapies targeting mutation-associated neoantigens (MANAs) are an alternative strategy to eliminate cancer cells harboring intracellular mutant oncoproteins, including KRAS." (PMID 37604828, 2023). "Blocking EGFR/KRAS signals is a major goal for cancer therapy and many new therapeutic approaches are currently being designed to target EGFR/KRAS activation." (PMID 37251335, 2023). "Although KRAS has been identified as an excellent drug target for many cancers, the direct inhibition of oncogenic KRAS has proven to be challenging due to the absence of druggable pockets on its surface." (PMID 37509241, 2023). "Our study reveals a novel PDE4DIP-mediated PKCε/NF1/RAS signal transduction axis and highlights PDE4DIP as a promising therapeutic target for KRAS-mutant cancers." (PMID 37355626, 2023). "Here, we demonstrate the utility of INCERTS for identifying potentially rare cancer-specific TCRs using peripheral blood mononuclear cells (PBMCs) from a set of patients receiving a novel mutant KRAS peptide vaccine." (PMID 37776855, 2023). "Here, we identified that ryanodine receptor 2 (RyR2) expression was upregulated in KRAS‐mutant mCRC, and that this promoted cancer cell metastasis." (PMID 36453019, 2023). "KRAS has always been considered as a therapeutic target in cancer but until now only two compounds that inhibit one specific KRAS mutation have been approved for clinical use." (PMID 36614192, 2023). "For specimen collection, patients were categorized as having KRAS G12C or KRAS WT cancer based on the closest specimen collection to index date (1L or 2L treatment initiation)." (PMID 37069542, 2023). "We examine the electrical detection of RNA cancer biomarkers (KRAS mutants G12C and G12V) as a single-molecule proof-of-concept electrical biosensor for cancer screening applications." (PMID 37528139, 2023). "YAP interacts with the FOS transcription factor at the promoters of EMT genes such as SNAIL2 in KRAS-driven cancer cells." (PMID 37835395, 2023). "Molecular information about KRAS status has important implications and should be considered in a more general picture of cancer patients in different phases of the disease, and it involves different doctors on the multidisciplinary team." (PMID 36836752, 2023). "Using these methods, we observed that KRAS is the most abundant isoform in a selection of cancer cell lines." (PMID 36864243, 2023). "The features within our K20 model offer a novel look into the genetic landscape of KRAS-dependent cancer cells." (PMID 37141389, 2023). "A higher proportion of patients in the KRAS-mutant group (5.7%) had a family history of cancer compared to the KRAS wild-type group (2.9%), where at least one case of cancer was reported in the family." (PMID 37761297, 2023).
cancer (continued). "We categorized patients with KRAS G12C, KEAP1, and STK11 mutational status using both solid and liquid assays; patients with cancer that was categorized as WT were assigned based on solid assays only." (PMID 37069542, 2023). "CCK8 assay result shown that the higher concentrations of KRAS led to lower anti-cancer effect of cetuximab." (PMID 36639711, 2023). "Cancer cells driven by KRAS release cytokines and other substances to regulate stromal cells, such as fibroblasts and innate and adaptive immune cells, in their vicinity." (PMID 36936437, 2023). "This suggests that rare codon-mediated limitation of Ras protein expression is not responsible for the much higher representation of mutants of KRAS than NRAS in human cancer patients." (PMID 36864243, 2023). "The novel MEK inhibitor tunlametinib in combination with KRASG12C inhibitor AMG510 demonstrated high activity in preclinical xenograft models of KRAS-mutant cancers, rendering a potentially effective treatment for RAS-mutant cancers in clinic." (PMID 37808191, 2023). "The targeting of KRAS has been extensively investigated since its discovery as an oncogene, and more earnestly after the discovery that KRAS-mutant cancers are resistant to anti-EGFR therapy." (PMID 37190303, 2023). "Immunoediting of neoantigens, reduced HLA expression and inactivation of the IFN-γ pathway are perhaps the most ubiquitous examples of immune evasion in KRAS-mutant PD-L1 + cancers, while acquired resistance to immunotherapies tends to be more nuanced." (PMID 36864508, 2023). "In recent years, a breakthrough in developing a direct inhibitor to target mutant KRAS G12C and G12D has been made, reviving hope for the specific targeting of KRAS mutant cancers." (PMID 38069255, 2023). "EFR3A-PI4KA interaction on the PM has been implicated in many KRAS-dependent tumors, and treatments with PI4KA inhibitors along with KRAS inhibitors, or MAPK and PI3K inhibitors have proved to improve efficacy in cancer cell growth inhibition." (PMID 38239314, 2023). "Most importantly, these inhibitors provide unequivocal proof of KRAS as a cancer drug target in humans." (PMID 36688434, 2023). "To this end, in this review, we summarize and discuss the recent insights in the deregulation of lipid metabolism of KRAS-driven tumors, as well as the interplay between specific lipids and key cancer machineries." (PMID 36675307, 2023). "The median (95% CI) OS in patients with KRASG12C-positive vs KRAS WT cancer treated with chemotherapy alone was 10.2 (8.0-12.5) months vs 8.3 (7.4-9.4) months (aHR, 0.92; 95% CI, 0.77–1.10; p = 0.37)." (PMID 37069542, 2023). "The main past and current strategies for developing therapeutics to block mutant KRAS function have focused on indirect approaches, which encompass selective targeting of proteins that support KRAS function and promote KRAS-driven cancer growth." (PMID 36835086, 2023). "ASP2453, a novel KRAS G12C inhibitor, showed antitumor efficacy in the preclinical models of KRAS G12C mutant cancers." (PMID 36675641, 2023). "Analogously to compound 13, the hydroxyquinoline derivative 15 (YUM70) was able to downregulate KRAS, leading to antiproliferative and pro-apoptotic effects on KRAS-mutant cancer cells." (PMID 36835501, 2023). "The goal of our study was to apply CANDO towards predicting novel drugs/compounds capable of synergizing with known KRAS inhibitors, and validate these findings using human cancer cell lines." (PMID 36674513, 2023). "The release of KRAS by cancer cells undergoing ferroptosis packaged in exosomes and absorbed by macrophages leads to an M2-like phenotype." (PMID 37569407, 2023). "Median OS was comparable between patients with KRAS G12C–positive and KRAS WT cancer when receiving chemotherapy or combination CIT and chemotherapy in the 1L or 2L." (PMID 37069542, 2023).
cancer (continued). "KRAS-driven cancer cells also scavenge branch chain amino acids such as isoleucine, valine, and leucine and convert them into acetyl-CoA to trigger the TCA cycle." (PMID 37110218, 2023). "Cancer cells with G12C or G12V KRAS show high levels of kinase activity and low levels of phosphorylated receptors compared with wild-type cell lines." (PMID 37111737, 2023). "To explore this goal, we employed PK5L1940 and BRAF cancer cells to compare results in both KRAS and BRAF mutant models in RAG1 KO mice." (PMID 37415974, 2023). "We aim to provide a thorough understanding of the potential of nucleic acid-based strategies in the field of KRAS mutant cancer therapeutics." (PMID 38069255, 2023). "The success of targeting KRAS for cancer therapy is limited by resistance due to compensatory mechanism, making combinatorial approaches attractive." (PMID 37816716, 2023). "There is an urgent need to identify effective inhibitors that can target and block oncogenic KRAS in cancers." (PMID 37822837, 2023). "HRAS-mutant cancers had a higher frequency of co-altered mutations (48.8%) in MAPK, PI3K, or RTK pathways genes compared to KRAS- and NRAS-mutant cancers (41.4% and 38.4%, respectively; p < 0.05)." (PMID 37503077, 2023). "The RAS family (HRAS, NRAS, KRAS) of oncogenes is a highly sought-after target for cancer therapies." (PMID 37604828, 2023). "The findings of the functional analysis demonstrated that several signaling pathways related to cancer, including Hedgehog, KRAS, and TGF‐β signaling pathways, were activated in samples with a low RMscore." (PMID 35635121, 2023). "Three rat sarcoma (RAS) gene isoforms, KRAS, NRAS, and HRAS, constitute the most mutated family of small GTPases in cancer." (PMID 37662925, 2023). "RAS (HRAS, KRAS, and NRAS), as the second largest mutated gene driver in various human cancers, has long been a vital research target for cancer." (PMID 37704624, 2023). "Through several rounds of peptide screening and optimisation, we report a 6 amino acid unit containing cyclic peptide (CRVLIR) named cyclo-CRVLIR that is capable of blocking the p110α/RAS interaction in vitro and in several KRAS cancer cell lines." (PMID 36732563, 2023). "Mutations in the KRAS gene and overexpression of protein products of the MYC and ARF6 genes occur frequently in cancer." (PMID 37158894, 2023). "All these suggested that PLK1 promoted the stability of c-Myc protein, and in turn, c-Myc directly enhanced PLK1 transcription, establishing a positive feedback circuit in KRAS-mutant cancer cells." (PMID 38104151, 2023). "In all patients at 1L initiation, 10.4% of patients with KRAS WT cancer and 16.7% of patients with KRAS G12C-positive cancer had brain metastasis." (PMID 37069542, 2023). "In the 2L setting, median OS in patients with KRAS G12C–positive vs KRAS WT cancer treated with CIT alone was 11.3 (8.1–13.8) months vs 7.6 (6.3–9.3) months (aHR, 0.79; 95% CI, 0.61–1.03; p = 0.08)." (PMID 37069542, 2023). "For patients with KRAS WT cancer across all treatment types in the 1L setting, significantly shorter median OS was observed in patients with mSTK11-mKEAP1 vs STK11 WT-KEAP1 WT (5.8 vs 10.1 months; aHR, 1.81; 95% CI, 1.44–2.26; p < 0.001)." (PMID 37069542, 2023). "In mini‐CDX models, 10 mg/kg THZ1 distinctly suppressed CAPAN2 (KRAS‐G12V) cancer cells, evident through both significantly reduced RFU and T/C (%) values compared with the vehicle control group on day 7 (p = .022)." (PMID 38037549, 2023). "Oncolytic virotherapy with various viruses has been shown to induce the antitumor effect against KRAS/BRAF-mutant cancers, including CRC." (PMID 37972012, 2023).
cancer (continued). "Early RNAi screens using isogenic cell models or panels of KRAS mutant/WT cancer cell lines to identify RAS synthetic lethal genes yielded different targets among different studies." (PMID 37221195, 2023). "The proto-oncogene Kirsten rat sarcoma homolog KRAS is a member of the RAS family of oncogenes and is the most commonly mutated across all cancers." (PMID 36674513, 2023). "The application of the PROTAC principle has demonstrated the feasibility of endogenous degradation of KRAS, potentially opening a path for its use in treating KRAS-induced cancers." (PMID 38090627, 2023). "The increased ratio of mutant versus wild type KRAS abundance that drove the cancer responses in that study is analogous to the observations here." (PMID 36864243, 2023). "A natural product, Kurarinone, which was reported to have anti-cancer activity against various cancers, was identified to decrease the protein level of KRAS by proteasomal degradation dependent on an E3 ubiquitin ligase WDR76." (PMID 37110848, 2023). "Consistent with the sweet-spot model, higher KRAS expression reduced carcinogen-induced tumorigenesis in mice and altered engagement with cancer signaling pathways." (PMID 36864243, 2023). "This happens in KRAS mutant cancer, where hexokinase 2 (HK2) overexpression has been shown to be a key player to divert glucose in ribonucleotide and fatty acids synthesis." (PMID 37180110, 2023). "Over the past years, despite inhibitors having shown remarkable clinical responses in KRAS-mutant cancers, resistance to KRAS inhibitors has eventually developed." (PMID 36694209, 2023). "Understanding the function of let-7g as a KRAS-repressing molecule makes it an essential target for developing therapeutic strategies for human cancers in which KRAS is overexpressed." (PMID 37759534, 2023). "KRAS, HRAS, and NRAS are the three most commonly mutated RAS isoforms with varying mutation rates in different cancers." (PMID 37662925, 2023). "Most PDAC tumors are driven by aberrant KRAS activity, and a line of evidence suggests that oncogenic KRAS signaling enhances glycolysis in cancer cells by increasing the expression of glycolytic enzymes, such as lactate dehydrogenase A (LDHA)." (PMID 37733442, 2023). "Phospho-ERK1/2 and phospho-Akt1/2/3 are known downstream effectors of KRAS in the MAPK signaling in cancer cell lines." (PMID 37051535, 2023). "PCZ, as primarly an antipsychotic and antiemetic medication, shows promise in cancer therapy by targeting specific cancer-related molecules, including KRAS mutants." (PMID 38074670, 2023). "Such cancer selectivity led us to explore the anticancer mechanism because CSCs and KRAS-mutant cancers are refractory to conventional chemotherapy and radiotherapy." (PMID 37402770, 2023). "Concerning the mechanism, these inhibitors demonstrate a stronger affinity for both BRAF homodimers and BRAF-CRAF heterodimers, yet they are less effective against CRAF, potentially suggesting reduced impact on KRAS-driven cancers." (PMID 38111008, 2023). "Cancer genome sequencing was performed in only two patients: one patient with an MSH6 mutation and one patient with a KRAS G12V mutation." (PMID 38260832, 2023). "KRAS is one of the most commonly mutated oncogenic drivers in LUAD that has yet to be fully conquered in cancer treatment given the challenge of inhibiting KRAS directly." (PMID 37335087, 2023). "Graphene-modified electrochemical genosensors have demonstrated capabilities for detecting cancer-related DNA mutations such as in BRAF, KRAS, and EGFR genes in liquid biopsy and patient tissue samples." (PMID 37764496, 2023). "The superior anti-cancer effect is attributed to the inhibition of the KRAS gene resulting in S-phase arrest of the cell cycle in Panc-1 cells." (PMID 36635659, 2023).
cancer (continued). "Mutation in a rat sarcoma virus (RAS) is associated with nearly 30% of the entire human cancers and accounts for almost 85% of Kirsten RAS (KRAS) of whole RAS mutations." (PMID 37371705, 2023). "Collectively, these data indicate that SLC25A21 inhibits cancer cell growth and metastasis by repressing the KRAS/AKT/ERK pathway in KRAS-mutant CRC." (PMID 37937641, 2023). "We detected two unique patterns of RNA modification and discovered that they were associated significantly with the cell cycle, KRAS, TGF‐β, and other signaling pathways related to cancer." (PMID 35635121, 2023). "Since KRAS proteins are inside the cancer cells, anti-KRAS antibodies must be able to enter the cytoplasm to bind to the KRAS molecules." (PMID 37051535, 2023). "The signaling networks of KRAS with other important pathways in cancer cells are well-documented, however the mechanisms of KRAS dependency remain poorly understood." (PMID 37141389, 2023). "This patient had two detectable cancer‐associated mutations in plasma at baseline, and while the level of the one with the highest AF (MET) was quite stable, the second (KRAS) reached undetectable levels during treatment." (PMID 36330681, 2023). "Collectively, these results encourage testing of the emerging PP2A-reactivating therapies for their impact on KRAS-mutant cancers in combination with epigenetic therapies." (PMID 36858798, 2023). "Despite the success of AMG-510 and MRTX849 in cancer with KRAS-G12C, quite a number of patients exhibit little objective response due to innate resistance." (PMID 37110848, 2023). "OVT is designed to target molecular markers which are overexpressed or dysregulated in cancer cells, in particular KRAS which is present in 90% of pancreatic cancer cases." (PMID 37686543, 2023). "The high mutation frequency of KRAS and its pivotal role in driving human oncogenesis and resistance to cancer therapies prompted the search for pharmacologic agents to thwart mutant (mt) KRAS." (PMID 38051103, 2023). "They promote oncogenic KRAS antitumor immunity by providing oncogenic KRAS neoantigens to MHC molecules which aim to develop cancer specific long term memory T cells." (PMID 37686543, 2023). "Overexpression or activation of PKCε occurs in numerous cancers and has been shown to be necessary for KRAS-driven lung tumorigenesis." (PMID 37355626, 2023). "The proof of principle for targeting KRAS protein as an anti-cancer strategy has been verified by the knockout of KRAS protein in both human and mouse cell lines." (PMID 37110848, 2023). "It is interesting that for patients receiving 1L CIT alone, median OS for patients with KRAS G12C-positive cancer is numerically longer than patients with KRAS WT cancer." (PMID 37069542, 2023). "KRAS inhibition or blockade of lactic acid production represents an exploitable approach to improve cancer immunotherapies." (PMID 36599679, 2023).